CCN2 (cellular communication network factor 2)
Diseases named in the same sentence as CCN2 in open-access papers (continued):
Sharing a sentence is not in itself a finding about the gene and the disease.
respiratory failure (6 papers, 2009 to 2025). The significant impairment of gas exchange within the lungs resulting in hypoxia, hypercarbia, or both, to the extent that organ tissue perfusion is severely compromised. "Ccn2 deficient mice exhibit perinatal lethality due to respiratory failure primarily attributed to short and bent sterna and kinked ribs." (PMID 39506047, 2025). "As a result of CCN2 deficiency, growth-plate angiogenesis and endochondral ossification are partially impaired, and CCN2-deficient mice die after birth because of respiratory failure caused by the skeletal defects." (PMID 23555635, 2013). "Regarding gene expression regulation, CCN2 knockout mice die shortly after birth by respiratory failure due to its essential role in coordinating chondrogenesis and angiogenesis during skeletal development." (PMID 35008801, 2021).
rhabdomyosarcoma (6 papers, 2014 to 2021). A rare aggressive malignant mesenchymal neoplasm arising from skeletal muscle. "CCN2 is expressed in spontaneous rhabdomyosarcomas of the genitourinary tract of Balbp53neu transgenic mice and human rhabdomyosarcoma cell lines of both alveolar and embryonal subtypes." (PMID 34228239, 2021). "For example, in human rhabdomyosarcoma, CCN2 has been demonstrated to be a useful therapeutic agent and disrupting CCN2 expression using CCN2-neutralizing antibodies can enhance apoptosis and inhibit angiogenesis." (PMID 24637722, 2014).
chronic pancreatitis (5 papers, 2015 to 2023). A chronic inflammatory process causing damage and fibrosis of the pancreatic parenchyma. "For example, dysregulation of Hippo signaling pathway induces chronic pancreatitis via CCN2 upregulation." (PMID 37973852, 2023). "A second confirmatory phase on an independent cohort of 131 PDAC patients, 30 chronic pancreatitis patients, and 131 healthy subjects confirmed the PDAC association for MMP7, CCN2, IGFBP2, TSP2, sICAM1, TIMP1, and PLG." (PMID 29941541, 2018). "Moreover, a panel consisting of CCN2, plasminogen (PGL), fibronectin, collagen 4 and CA19.9 was found able to distinguish PDAC from chronic pancreatitis patients." (PMID 30678058, 2019).
endothelial dysfunction (5 papers, 2022 to 2025). In vascular diseases, endothelial dysfunction is a systemic pathological state of the endothelium (the inner lining of blood vessels) and can be broadly defined as an imbalance between vasodilating and vasoconstricting substances produced by (or acting on) the endothelium. "Previous studies have demonstrated that CCN2 causes endothelial dysfunction in ex vivo isolated aortic rings and in mice, supporting these findings." (PMID 40362638, 2025). "In an early study, we described that CCN2 can induce endothelial dysfunction in mouse aorta." (PMID 40362638, 2025).
gastric adenocarcinoma (5 papers, 2005 to 2020). "CCN2 (Cyr61) stimulates the growth of breast and gastric adenocarcinomas, whereas its expression is downregulated in non-small cell lung cancer, in which CCN2 suppressed the growth of NSCLC cells by triggering a signal transduction pathway through β-catenin." (PMID 16457688, 2005).
invasive breast carcinoma (5 papers, 2016 to 2023). A carcinoma that infiltrates the breast parenchyma. "There was no significance of DNA promoter methylation between invasive breast cancer and normal breast tissues in 4 upregulated hub genes (MAD2L1, FEN1, CDKN3, CCN2)." (PMID 31777591, 2019).
osteoporosis (5 papers, 2018 to 2025). A condition of reduced bone mass, with decreased cortical thickness and a decrease in the number and size of the trabeculae of cancellous bone (but normal chemical composition), resulting in increased fracture incidence. "The results of the study predicted that higher serum levels of CCN1 are associated with an increased risk of osteoporosis in both UK Biobank and FinnGen datasets, while the former also projected a negative association between serum CCN2 and osteoporosis risk." (PMID 40407982, 2025). "Further studies are required and expected to determine whether modulating CCN2 could provide a new therapeutic approach for osteoporosis." (PMID 39414788, 2024).
carcinoid heart disease (4 papers, 2010 to 2021). Cardiac manifestation of gastrointestinal CARCINOID TUMOR that metastasizes to the liver. "We sought to investigate the relationship between plasma CCN2 and valvular and mural involvement in carcinoid heart disease." (PMID 20053285, 2010).
chronic lung disease (4 papers, 2007 to 2019). According to the definitions of the American and British Thoracic Societies, including pulmonary functional tests, X-rays, and CT scans for items such as fibrosis, bronchiectasis, bullae, emphysema, nodular or lymphomatous abnormalities. "Connective tissue growth factor (CTGF, CCN2) plays a key role in airway remodeling and has been implicated in the pathogenesis of chronic lung diseases such as bronchopulmonary dysplasia (BPD) in preterm infants." (PMID 28330503, 2017).
depression (4 papers, 2019 to 2022). "CCN2 (CTGF) has recently been implicated as a prodepressant molecule on the basis of human and animal model studies, while CCN3 hippocampal expression is decreased ∼1.7-fold in the “chronic social defeat” mouse model of depression." (PMID 31849729, 2019).
liver cirrhosis (4 papers, 2012 to 2021). "However, additional experiments, e.g. elimination studies in experimental liver cirrhosis, would be needed to explore the postulated contribution of reduced hepatic removal to elevated CCN-2 levels in chronic liver disease." (PMID 27644406, 2016).
pancreatic ductal adenocarcinoma (4 papers, 2016 to 2021). An infiltrating adenocarcinoma that arises from the epithelial cells of the pancreas. "In pancreatic ductal adenocarcinoma, CCN2 signaling induces stromal infiltration and facilitates a strong tumor-stromal interaction." (PMID 27613407, 2016). "In preclinical studies of pancreatic ductal adenocarcinoma (PDAC), a cancer type with particularly strong tumor-stroma interaction and stromal infiltration, CCN2 has been identified as a major determinant of tumor growth and metastasis, and as a valid therapeutic target." (PMID 27613407, 2016).
serous ovarian cancer (4 papers, 2015 to 2023). "We performed the qRT-PCR analysis of TGFβ components (TGFB1, TGFB2, TGFBR1, TGFBR2), Wnt5A/ROR1/ROR2, and Hippo-related genes (YAP1, TAZ, CCN1, and CCN2) in serous ovarian cancer subtypes (LGSOC, HGSOC, BLSOC) compared to the normal ovary." (PMID 35053353, 2022).
steatosis (4 papers, 2016 to 2025). Increased lipid within the cytoplasm of cells. "However, liver histology and expression of collagen or TGF-β1 in fa/fa rats were normal and comparable to Fa/fa rats leading the investigators to conclude that CCN2-mediated fibrosis required the presence of other pathological hits such as steatosis or inflammation." (PMID 37629004, 2023). "In rhesus monkeys fed HFD for 2 years, expression of hepatic CCN2, TGF-β αSMA, and Smad 3 were increased in simple steatosis compared to healthy controls and in fibrosing NASH compared to simple steatosis, with CCN2 correlating positively with the severity of fibrosis." (PMID 37629004, 2023).
acute myeloid leukemia (3 papers, 2016 to 2024). Acute myeloid leukemia (AML) is a group of neoplasms arising from precursor cells committed to the myeloid cell-line differentiation. "In acute myeloid leukemia, CCN2 expression is increased in MSCs, which has been associated with leukemic engraftment in vivo." (PMID 33428075, 2021). "MSCs isolated from the BM of acute myeloid leukemia (AML)-bearing mice showed increased CCN2 expression compared with MSCs from control mice." (PMID 33428075, 2021). "Further work using quantitative PCR and microarrays confirmed high CCN2 expression in lymphoblasts in adult ALL and allowed discrimination from Acute Myeloid Leukaemia (AML)." (PMID 27485291, 2016).
ameloblastoma (3 papers, 2021 to 2024). The most common odontogenic tumor, arising from the epithelial component of the embryonic tooth and usually affecting the molar-ramus region of the mandible or maxilla. "It was recently shown that parenchyma–stromal CCN2 overexpression positively correlated with fibrous-type stroma, suggesting a role of CCN2 in fibrosis induction in ameloblastoma." (PMID 34205668, 2021).
cardiac ischemia (3 papers, 2019 to 2022). "Similar to CCN2, myocardial CCN1 and CCN4 also respond as immediate early genes and reach peak levels of expression during the inflammatory phase after onset of myocardial ischemia." (PMID 34854055, 2022).
head and neck cancer (3 papers, 2017 to 2022). A primary or metastatic malignant neoplasm affecting the head and neck. "A study of patient-derived tumor samples in the Cancer Genome Atlas database showed that CCN2 expression was higher in head and neck cancers, and high expression of CCN2 and MMP3 was associated with worse prognosis in head and neck cancers." (PMID 35042954, 2022).
Hydrocephalus (3 papers, 2021 to 2024). Hydrocephalus is an active distension of the ventricular system of the brain resulting from inadequate passage of CSF from its point of production within the cerebral ventricles to its point of absorption into the systemic circulation. "We identified rhythmically expressed genes, which have been associated with developmental processes, such as hydrocephalus-associated genes (Ccdc88c, Hydin), and several rhythmically expressed mitogens, which are likely diurnally released into CSF (Wnt5b, Angpt1-2, Ccn2)." (PMID 38802875, 2024).
infarct (3 papers, 2012 to 2021). "The main objectives of the study were therefore to investigate whether circulating CCN2 levels were associated with infarct size, LV function, adverse remodelling or clinical outcome in two cohorts of patients with ST-elevation myocardial infarction (STEMI)." (PMID 28931920, 2017). "Increased expression of CCN2 in cardiac myocytes and fibroblasts following MI has been demonstrated in several experimental models, indicating a role of CCN2 in post-infarction fibrosis." (PMID 28931920, 2017). "Interestingly, in these models, telmisartan reduced CCN2/CTGF levels only if the treatment was started at the beginning of infarction." (PMID 34063397, 2021). "We may have missed the peak value, and it is possible that the main effects of CCN2 occur during the first weeks/months rather than hours/days after the infarction." (PMID 28931920, 2017).
ischemia reperfusion injury (3 papers, 2016 to 2022). Adverse functional, metabolic, or structural changes in ischemic tissues resulting from the restoration of blood flow to the tissue (reperfusion), including swelling; hemorrhage; necrosis; and damage from free radicals. "Concordantly, the post-ischemic administration of recombinant human CCN2 increased the tolerance of ex vivo-perfused murine hearts to ischemia reperfusion injury." (PMID 36499730, 2022). "Previous studies of ischemia-reperfusion injury (IRI) in hearts from mice with cardiac-restricted overexpression of CCN2 have shown that CCN2 increases tolerance towards IRI." (PMID 26872261, 2016).
metastatic cancers (3 papers, 2011 to 2020). A carcinoma which has spread from the original site of growth to another anatomic site. "Given these functions of CCN2, in pathological states where the expression of CCN2 is elevated, CCN2 expression is commonly associated with increased fibrotic responses and chemotherapeutic-resistant metastatic cancers." (PMID 30029495, 2018).
pancreatitis (3 papers, 2018 to 2022). Inflammation of the pancreas. "Notably, herein the identified CCN2 + PLG+FN+Col4 + CA19.9 panel appeared to have a higher capability in discriminating PDAC from pancreatitis (AUC = 0.94) than the recently proposed TIMP1 + LRG1 + CA19.9 panel (AUC = 0.89)." (PMID 29941541, 2018).
pseudoexfoliation glaucoma (3 papers, 2016 to 2023). "CCN2/CTGF itself is present in the aqueous humor and has been described to be increased in patients with POAG and pseudoexfoliation glaucoma." (PMID 37251082, 2023). "In the aqueous humor CCN2/CTGF is a general component, furthermore CCN2/CTGF levels are increased in patients with pseudoexfoliation glaucoma." (PMID 35493079, 2022).
tongue squamous cell carcinoma (3 papers, 2020 to 2025). A squamous cell carcinoma that arises from the tongue. "CCN2 is expressed at higher levels in tongue squamous cell carcinoma tissues than in paraneoplastic tissues, and its expression correlated with lymph node metastasis." (PMID 35042954, 2022). "Moreover, mesenchymal stem cell-derived CCN2 promoted tongue squamous cell carcinoma progression in vitro and in vivo." (PMID 35042954, 2022). "MSC-derived CCN2/CTGF promoted tongue squamous cell carcinoma progression." (PMID 32260433, 2020). "In a separate study, the upregulation of a connective tissue growth factor, CCN2, was identified in tongue squamous cell carcinoma samples." (PMID 41511327, 2025).
Anxiety (2 papers, 2019 to 2024). Intense feelings of nervousness, tension, or panic often arise in response to interpersonal stresses. "We showed for the first time that male mice lacking the Ccn2 gene in the forebrain exhibit signs of anxiety and elevated reactive aggression but normal locomotion, sensorimotor gating, and social behaviors." (PMID 39524137, 2024). "Our study characterized for the first time that mice lacking CCN2 in the forebrain display signs of anxiety and elevated reactive aggression." (PMID 39524137, 2024). "Male mice lacking CCN2 in the forebrain exhibited normal locomotion, sensorimotor gating, and social behaviors but signs of anxiety and elevated reactive aggression." (PMID 39524137, 2024). "Taken together, mice lacking Ccn2 exhibit normal locomotion and sensorimotor gating properties but anxiety‐like behavior in a sex‐dependent manner." (PMID 39524137, 2024). "Further, lacking CCN2 in the prefrontal cortex, the major area related to inhibitory control and emotion regulation, may lead to signs of anxiety and the failure to suppress aggressive behaviors." (PMID 39524137, 2024). "CCN2 expression in the mPFC and OFC is absent in male FbCcn2−/− mice which display signs of anxiety." (PMID 39524137, 2024).
Blindness (2 papers, 2008 to 2022). Blindness is the condition of lacking visual perception defined as a profound reduction in visual perception. "Vascular endothelial growth factor (VEGF) and connective tissue growth factor (CCN2/CTGF) contribute to blindness through their promotion of neovascularization and subsequent fibrosis." (PMID 36111346, 2022).
cholangiocarcinoma (2 papers, 2021 to 2022). A carcinoma that arises from the intrahepatic biliary tree (intrahepatic cholangiocarcinoma) or from the junction, or adjacent to the junction, of the right and left hepatic ducts (hilar cholangiocarcinoma). "In human cholangiocarcinoma, ZEB1 is expressed in CAFs, correlating with cellular communication network factor 2 (CCN2) gene (encoded for CTGF) expression." (PMID 35159011, 2022).
colorectal adenocarcinoma (2 papers, 2020 to 2025). The most common type of colorectal carcinoma. "We next examined the co-expression correlation between MMP3 and CCN2/CTGF among 632 tumor samples derived from 632 colorectal adenocarcinoma patients registered in The Cancer Genome Atlas (TCGA)." (PMID 32260433, 2020). "There was a marked co-expression correlation significance between MMP3 and CCN2/CTGF (y = 0.08x + 0.1, R2 = 0.06) in the colorectal adenocarcinoma cases, suggesting that MMP3 may positively regulate CCN2/CTGF expression in both human clinical tumors and mouse cancers." (PMID 32260433, 2020).
Diabetic Foot Ulcer (2 papers, 2015). "This is the first time that changes in endogenous CTGF/CCN2 have been reported in human diabetic foot ulcers or related ulcer fluid." (PMID 25789327, 2015).
gingival hyperplasia (2 papers, 2011 to 2024). "Fibroproliferative conditions (e.g gingival hyperplasia) are well-known to affect thegingiva and, in these conditions, CCN2/CTGF is overexpressed." (PMID 21611193, 2011).
Hypercholesterolemia (2 papers, 2023 to 2024). An increased concentration of cholesterol in the blood. "Deficiency of CCN2 in SMC exacerbates Ang II–induced AAA in hypercholesterolemia mice." (PMID 36625347, 2023). "Transcriptomic analysis highlighted that paternal hypercholesterolemia stimulated proatherogenic genes, including Ccn1 and Ccn2, in the intima of female offspring." (PMID 39253968, 2024).
intervertebral disc degeneration (2 papers, 2018 to 2025). "Our results suggested that the decrease of active TGF-β is associated with its downstream anabolic CCN2-ECM cascade during age-related intervertebral disc degeneration." (PMID 30038820, 2018). "Previous studies have demonstrated that CCN2 plays a pivotal regulatory role in the progression of intervertebral disc degeneration." (PMID 40963934, 2025).
lymphoma (2 papers, 2016 to 2023). A malignant (clonal) proliferation of B- lymphocytes or T- lymphocytes which involves the lymph nodes, bone marrow and/or extranodal sites. "CCN2 has been shown to be highly expressed in cells from patients with Hodgkins (44 patients) compared to non-Hodgkins (32 patients) lymphoma." (PMID 27485291, 2016).
myelofibrosis (2 papers, 2021 to 2024). A partial or complete replacement of the bone marrow stroma by fibrous tissue. "CCN2 staining was found in a higher percentage of megakaryocytes in biopsies of myelofibrosis patients compared to controls (63% vs 40%)." (PMID 38602559, 2024). "Furthermore, CCN2 mRNA extracted from BM biopsies of patients with myelofibrosis showed a 27-fold increase when compared to healthy controls, decreasing after allogeneic stem cell transplantation." (PMID 38602559, 2024). "In addition, no appreciable CCN2 was detected in normal megakaryocytes in vivo, although immunohistochemical staining indicated strong expression of CCN2 in megakaryocytes of primary myelofibrosis and in a subpopulation of megakaryocytes in patients with X-linked thrombocytopenia with thalassemia." (PMID 33428075, 2021). "CCN2 can promote fibrosis directly or by acting as a factor downstream of TGF-β, the latter already known to contribute to myelofibrosis in MPN." (PMID 38602559, 2024). "A lack of correlation between CCN2 expression and BM fibrosis is remarkable, especially because the prototypical fibrosis inducer TGF-β, known to also contribute to myelofibrosis in MPN, is a potent inducer of CCN2, the two forming a positive feedback loop." (PMID 38602559, 2024). "Our data suggest that CCN2 is not a key driver of myelofibrosis in MPN, and that noncanonical, CCN2 independent, rather than canonical TGF-β signaling might be responsible for the development of fibrosis in MPN." (PMID 38602559, 2024).
retinal detachment (2 papers, 2020 to 2022). An eye emergency condition which may lead to blindness if left untreated. "In fact, CCN2/CTGF accumulates in the subretinal fluid of retinal detachment patients even before the onset of PVR." (PMID 32429045, 2020). "CCN2/CTGF has also been portrayed as a fibrotic factor and a high CCN2/VEGF ratio in eyes with proliferative DR tips the balance from neovascularization to fibrotic membrane formation, ultimately leading to fibrovascular membrane contraction and tractional retinal detachment." (PMID 32429045, 2020).
thoracic aortic aneurysm (2 papers, 2013 to 2022). An aneurysm formed in the wall of the proximal portion of the descending aorta proceeding from the arch of the aorta. "In order to translate these findings to humans, we evaluated the potential association between three polymorphisms in the CCN2 gene and the presence of a thoracic aortic aneurysm (TAA)." (PMID 36499730, 2022).